ZNF606 (zinc finger protein 606)
Description:
May act as a transcriptional repressor.
Synonyms: KIAA1852; ZNF328; FLJ14260
Tractability: No criterion of Open Targets' tractability assessment is met for any kind of drug.
Gene: Protein-coding gene on chromosome 19 (57,977,076 to 58,003,349, reverse strand). Ensembl gene ENSG00000166704.
Subcellular location: Nucleus
Subcellular location (Human Protein Atlas): Nucleoplasm
Pathways (Reactome):
Gene expression (Transcription): Generic Transcription Pathway
Gene Ontology:
Molecular function: transcription cis-regulatory region binding
Biological process: regulation of transcription by RNA polymerase II; regulation of DNA-templated transcription
Cellular component: nucleoplasm; nucleus
Genetic constraint (gnomAD): Loss-of-function variants: 37 observed, 78.4 expected, observed/expected ratio (o/e) 0.47, 90% interval 0.36 to 0.62. The upper end of that interval is the gene's LOEUF score, 0.62, which puts it in group 2 of 6, group 1 being the genes least tolerant of losing a copy. Missense variants: 852 observed, 1,005.1 expected, observed/expected ratio (o/e) 0.85, 90% interval 0.8 to 0.9. Synonymous variants: 328 observed, 330.76 expected, observed/expected ratio (o/e) 0.99, 90% interval 0.9 to 1.09.
Homologues: Orthologues: chimpanzee ZNF606 (99% identical), macaque ZNF606 (99% identical), dog ZNF606 (94% identical), rabbit ZNF606 (91% identical), pig ZNF606 (91% identical), mouse Zfp606 (89% identical), guinea pig ZNF606 (87% identical). Paralogues in human: ZNF33B (39% identical), ZNF658 (38% identical), ZNF28 (36% identical), ZNF568 (36% identical), ZNF841 (36% identical), ZNF585B (36% identical), ZNF234 (35% identical), ZNF484 (35% identical), ZNF726 (35% identical), ZNF33A (35% identical), ZNF41 (35% identical), ZNF595 (35% identical), and 164 more.
Diseases named in the same sentence as ZNF606 in open-access papers:
ZNF606 is named in the same sentence as 4 diseases in open-access papers, as found by Europe PMC text mining. Sharing a sentence is not in itself a finding about the gene and the disease. The quoted sentences say what the papers report.
colon adenocarcinoma (1 paper, 2017). "Validation of these regions in the TCGA colon adenocarcinoma data identified a signature of 4 genes; ELOVL5, FAM127B, MTERF1 and ZNF606, which are downregulated in hypermethylated tumors." (PMID 28931069, 2017).
coronary artery disease (1 paper, 2022). "A previous study demonstrated an association between ZNF606 gene expression from monocytes and the risk of coronary artery disease (CAD), especially in patients with multiple coronary artery stenosis." (PMID 35157609, 2022).
tumor (1 paper, 2017). "Overall, the transcriptional downregulation of ELOVL5, MTERF1 and ZNF606 shows potentially beneficial effect for the tumor cells." (PMID 28931069, 2017).
ZNF606 also shares sentences with these, for which no sentence is quoted: glioma (1 paper).